SPINK1 (serine peptidase inhibitor Kazal type 1)
Diseases named in the same sentence as SPINK1 in open-access papers (continued):
Sharing a sentence is not in itself a finding about the gene and the disease.
pancreatic cancer (continued). "Analysis of oxaliplatin, a platinum drug, revealed that the SPINK1 pancreatic cancer pathway is inactivated in ischemic cardiomyopathy." (PMID 38003016, 2023). "In pancreatic cancer, K73-03 upregulates miR-421 and downregulates SPINK1 through epigenetics, thereby inhibiting mitochondrial function and inducing autophagy and apoptosis." (PMID 35223512, 2022). "In the low group, SPINK1 Pancreatic Cancer Pathway was the most significantly activated pathway (z score: 1.155, p value: 3.82E−8, ratio: 0.2)." (PMID 35780404, 2022). "Previous studies have shown co-expression of SPINK1 and EGFR in pancreatic tumors and SPINK1 promote pancreatic cancer cells through the mitogen-activated protein kinase (MAPK) pathway in vitro." (PMID 36053457, 2022). "The highly inhibited SPINK1 pancreatic cancer pathway (z = − 2.813) was most significantly annotated in the canonical pathway." (PMID 36038612, 2022). "Over the last decade, the genetics associated with pancreatic cancer has been intricately assessed Some well-known cancer gene germline mutations have been identified in patients with pancreatic cancer, including BRCA1/2, PALB2, STK11, PRSS1, SPINK1 and ATM." (PMID 35813042, 2022). "SPINK1 overexpression enhances resistance to gemcitabine (GCB) (a first-line chemotherapy drug for pancreatic cancer)." (PMID 35223512, 2022). "The top pathways suggested tRNA splicing, vitamin C transport, apelin liver signaling, metabolism of aryl hydrocarbon receptor (AHR) signaling, glycoprotein VI platelet (GP6) signaling, and SPINK1 pancreatic cancer pathway." (PMID 34685781, 2021). "Using a z-score cutoff of magnitude 2, IPA showed activation of “glycolysis I”, “gluconeogenesis I”, “protein kinase A signaling”, “NRF2-mediated oxidative stress response”, and “SPINK1 pancreatic cancer pathway” in the overall PDR versus control comparison." (PMID 34861815, 2021). "In pancreatic cancer cell lines, SPINK1 was coprecipitated with EGFR in an immunoprecipitation experiment and trigger cancer cell proliferation via activating EGFR downstream signaling." (PMID 33916984, 2021). "For example, SPINK1 in pancreatic cancer has several potentially important clinical applications ranging from a biomarker to a potential new target for cancer therapy." (PMID 34055623, 2021). "Lentiviral-based stable SPINK1 overexpression also increased the proliferative capacity of the AsPC-1 human pancreatic cancer cell line." (PMID 33916984, 2021). "The main canonical pathways involved were SPINK1 Pancreatic Cancer Pathway (−log (P value) = 4.45, ratio = 0.0667) and Circadian Rhythm Signaling (−log (P value) = 2.33, ratio = 0.0606)." (PMID 34721627, 2021). "RNA-Seq revealed the mechanism of DOP to inhibit MNNG-induced PLGC in the rat model; the main canonical pathways were SPINK1 Pancreatic Cancer Pathway and Circadian Rhythm Signaling." (PMID 34721627, 2021). "“Serine protease inhibitor, Kasal type 1 (SPINK1) pancreatic cancer pathway” was activated in PDR vitreous." (PMID 34861815, 2021). "The increased pancreatic cancer cell proliferation by SPINK1 was further reported of which mechanism was through EGFR-mediated signaling activation." (PMID 33916984, 2021). "The main canonical pathways were SPINK1 Pancreatic Cancer Pathway (−log (P value) = 4.45, ratio = 0.0667) and Circadian Rhythm Signaling (−log (P value) = 2.33, ratio = 0.0606)." (PMID 34721627, 2021). "Here, we identified the serine protease inhibitor Kazal-type 1 (SPINK1) pathway as most interesting and relevant with regard to pancreatic cancer development." (PMID 33328982, 2020). "The majority of the pathways are down‐regulated in AS tumors except for the SPINK1 pancreatic cancer pathway and the SPINK1 general cancer pathway." (PMID 32920960, 2020).
pancreatic cancer (continued). "Cathepsin B is also a key player in the SPINK1 (serine protease inhibitor Kazal-type 1) pathway leading to pancreatic cancer." (PMID 33328982, 2020). "In pancreatic cancer, SPINK1 overexpression leads to gemcitabine resistance." (PMID 40904507, 2025). "Chronic alcoholic pancreatitis displays a cumulative risk of pancreatic cancer estimated at 4% after 15 to 20 years, this risk being higher for hereditary pancreatitis with 19% and 12% in the case of PRSS1 and SPINK1 mutations, respectively, and at an age of 60 years." (PMID 36765725, 2023). "CRSsNP specific were SPINK1 pancreatic cancer pathway and LXR/RXR activation." (PMID 36982612, 2023). "The top five pathways according to p value were SPINK1 Pancreatic Cancer Pathway, BAG2 Signaling Pathway (p = 9.20E−8), Aryl Hydrocarbon Receptor Signaling (p = 4.22E−7), Clathrin-mediated Endocytosis Signaling (p = 7.81E−7), and Protein Ubiquitination Pathway (p = 8.22E−7)." (PMID 35780404, 2022). "The top five pathways according to p value were SPINK1 Pancreatic Cancer Pathway, EIF2 Signaling (p = 1.05E−7), Aryl Hydrocarbon Receptor Signaling (p = 1.05E−7), Clathrin-mediated Endocytosis Signaling (p = 2.3E−7), and Actin Cytoskeleton Signaling (p = 2.44E−7)." (PMID 35780404, 2022). "Furthermore, CP is also a risk factor for pancreatic cancer and patients with hereditary pancreatitis associated with SPINK1 and SPINK2 mutations have a 40% lifetime risk of developing pancreatic cancer." (PMID 36500723, 2022). "The SPINK1 pancreatic cancer pathway was the main pathway expressed following the 24 h triclosan exposure and 120 h 4-nonylphenol exposure, and includes genes such as carboxypeptidase A1 (pancreatic; cpa1), which was dysregulated at 1 nM triclosan, and 10 and 1000 nM 4-nonylphenol." (PMID 35202241, 2022). "The top canonical pathways of Cluster 1 included pancreatic cancer initiation pathways, including SPINK1 Pancreatic Cancer Pathway48, and multiple normal pancreatic function related pathways, including FXR/RXR Activation49,50, Apelin Adipocyte Signaling Pathway51,52 and Retinol Biosynthesis53,54." (PMID 35941362, 2022). "Also, three pathways including SPINK1 pancreatic cancer pathway, PTEN signaling, and inhibition of matrix metalloproteases were enriched in GSE116347 CT26 tumor Treg." (PMID 34084175, 2021). "Although PRSS1 and CPA1 variants have been linked to pancreatic cancer risk, to date variants in other chronic pancreatitis susceptibility genes such as SPINK1 and CFTR have not been consistently found to be risk factors for pancreatic cancer." (PMID 28881607, 2017). "Mutations in the high penetrance genes such as BRCA2, PALB2, p16/CDKN2A, PRSS1, SPINK1, and STK11 correlate with a very high lifetime risk of developing pancreatic cancer and may cause as many as 10% of pancreatic cancers in the US." (PMID 24883056, 2014). "The SPINK1 gene is normally not expressed outside of the pancreas, but its expression has been demonstrated to be elevated in pancreatic cancer, whereas the present study demonstrated that SPINK1 is highly expressed in normal pancreatic tissue compared with pancreatic cancer." (PMID 21245863, 2011). "Interestingly, SCK vs. NK comparison in SAT samples reveals that during ketosis, most of the genes within the SPINK1 Pancreatic Cancer Pathway relate to AT breakdown and are comparatively upregulated in VAT and downregulated in SAT, emphasizing depot-specific events of lipid mobilization during SCK." (PMID 40599780, 2025). "However, the relationship between SPINK1 and the development of pancreatic cancer is controversial." (PMID 33901011, 2021). "In this study, a four-gene prognostic signature that included SPINK1, ANO1, DSG3, and GIMAP1 in patients with pancreatic cancer were identified." (PMID 33901011, 2021). "Even in comparing the non-tumor and the high group, SPINK1 Pancreatic Cancer Pathway was the most significantly activated pathway (z score: 1.732, p value: 6.41E−8, ratio: 0.2)." (PMID 35780404, 2022).
pancreatic cancer (continued). "Moreover, our study shows that c-di-AMP+Pg LPS also significantly regulated non-inflammatory pathways such as SPINK1 pancreatic cancer pathway." (PMID 39669221, 2025).
hereditary pancreatitis (29 papers, 2010 to 2025). "SPINK1 mutations are associated with hereditary pancreatitis, but they often require an environmental or immune-mediated trigger to manifest clinically." (PMID 40605893, 2025). "PRSS1 and SPINK1 are associated with hereditary pancreatitis as well as PDAC and should be included in panels based on clinical features." (PMID 39860372, 2025). "We present the case of a 19-year-old woman who presented with vomiting and abdominal pain and was later diagnosed with hereditary pancreatitis following the detection of a heterozygous SPINK1 gene mutation." (PMID 40605893, 2025). "The study demonstrated a diagnostic-yield for FPC (3%), PRSS1/SPINK1 (hereditary pancreatitis; 4%), CDKN2A (FM) (5%), BRCA1/2 and PALB2 (HBOC) (6.3%), and STK11/LKB1 (Peutz–Jeghers syndrome; PJS; 12.2%)." (PMID 38619782, 2024). "The risk in SPINK1 and other mutations associated with hereditary pancreatitis is less well studied, but Muller and colleagues in their study including individuals with the SPINK1 pathogenic variant found a 12-fold increase in PDAC risk." (PMID 36140157, 2022). "In a broader sense, hereditary pancreatitis can be also caused by mutations in other genes (e.g., SPINK1), which are associated with autosomal recessive inheritance." (PMID 36140157, 2022). "The upgraded pathogenic variants include LRRK2 rs34637584 associated with autosomal dominant Parkinson disease 8 and SPINK1 rs148954387 associated with hereditary pancreatitis, both identified in one European-descent participant each." (PMID 31797629, 2020). "It is vital that patients who test positive for hereditary pancreatitis, including the SPINK1 mutation undergo active surveillance for pancreatic malignancy due to them being in a high-risk group." (PMID 29515728, 2017). "The IVS3 + 2 T > C mutation in SPINK1 was often noted in Korean patients with idiopathic and familial pancreatitis." (PMID 26100556, 2015). "Mutations in PRSS1 (cationic trypsinogen gene) are the underlying cause for hereditary pancreatitis and mutations in SPINK1 (serine protease inhibitor Kazal type I) are often found in patients with chronic or acute forms of the disease." (PMID 22216129, 2011). "However, as far as we are concerned, SPINK1 mutations have also been recognized as closely related to familial pancreatitis." (PMID 28348582, 2017). "Mutations in SPINK1 associate with hereditary pancreatitis and tropical calcific pancreatitis." (PMID 29383125, 2017). "The coexistence of SPINK1-related hereditary pancreatitis and active SLE in this patient illustrates how overlapping genetic and immune mechanisms can complicate the clinical picture, influence diagnostic priorities, and guide treatment decisions." (PMID 40605893, 2025). "This study also calculated the NNS for specific HRI groups, with a NNS of 250 for a PV in BRCA genes, 130 for PRSS1/SPINK1 (hereditary pancreatitis), 71 for STK11/LKB (PJS) and 51 for a PV in the CDKN2A gene." (PMID 38619782, 2024). "Pancreatectomy becomes advisable in case of proven idiopathic hereditary pancreatitis and identified mutations in the PRSS1, CFTR, SPINK1, or CTRC genes, especially when there is a risk of ductal adenocarcinoma." (PMID 39896151, 2024). "Numerous analyses in the literature focus on familial pancreatitis, for which many significant genetic mutations have been successfully described, including those in the PRSS1 and SPINK1 genes." (PMID 39457082, 2024). "Of those with hereditary pancreatitis, variants in the PRSS1 and SPINK1 genes were the most prevalent (16/22, 74% of individuals)." (PMID 39337011, 2024). "This cumulative risk is higher in hereditary pancreatitis: 19 and 12% in the case of PRSS1 and SPINK1 mutations, respectively, at an age of 60 years." (PMID 36765725, 2023). "Genetic testing for PRSS1 and SPINK1 in patients with hereditary pancreatitis has been reported in Europe and the US." (PMID 35994093, 2022).
hereditary pancreatitis (continued). "In the Japan National Survey of Hereditary Pancreatitis, mutations in PRSS1 were found in 30 of 73 families (41.1%) and mutations in SPINK1 in 26 (35.6%)." (PMID 35994093, 2022). "A failure to express this trypsinogen inhibitor, pancreatic secretory trypsin inhibitor (PSTI), also known as serine protease inhibitor Kazal type 1 (SPINK1), is a known cause of familial pancreatitis." (PMID 36452348, 2022). "He underwent genetic testing for various genes known to cause hereditary pancreatitis: CASR, CFTR, CTRC, PRSS1, SPINK1." (PMID 29515728, 2017). "For hereditary pancreatitis, heterozygous variants in two mechanistically genes of ‘trypsin-dependent pathway’, PRSS1 (encoding cationic trypsinogen) and SPINK1 (encoding pancreatic secretory trypsin inhibitor products), are said to have the effect of occurring human pathogenic variants." (PMID 37813108, 2023). "In addition, alterations in the activity of trypsinogen cause hereditary pancreatitis resulting from ER stress, such as mutations in the PRSS1 and SPINK1 genes." (PMID 34954140, 2022). "Notably, our results demonstrated that genetic predisposition toward chronic hereditary pancreatitis and pancreatic carcinogenesis, which involve PRSS1 and SPINK1, in BTC patients was associated with susceptibility to germline mutations." (PMID 33754015, 2021).
acute pancreatitis (20 papers, 2013 to 2025). An acute inflammatory process that leads to necrosis of the pancreatic parenchyma. "The patient was enrolled to the study on April 5, 2024 with the following diagnosis: hereditary calcifying pancreatitis (homozygous mutation c.101A>G of the SPINK1 gene), clinical phenotype — recurrent acute pancreatitis." (PMID 39896151, 2024). "When we meta-analyzed MVP GWAS and UK Biobank, we observed nine independent acute pancreatitis associated variants, with the top signal near SPINK1." (PMID 38491158, 2024). "CTRC polymorphism Hetero p.G60=; c.180C > T increases the risk of developing acute pancreatitis, and in combination with the SPINK1 mutation, can be responsible for a more severe course of the disease." (PMID 28095786, 2017). "The researchers concluded that the p.N34S mutation in SPINK1 may increase susceptibility to acute pancreatitis." (PMID 26100556, 2015). "Mutation p.N34S in SPINK1 may predispose patients to acute pancreatitis, especially in those abusing alcohol, and may promote a more severe course of the disease." (PMID 26100556, 2015). "The results of studies of p.N34S SPINK1 mutation in acute pancreatitis are divergent." (PMID 26100556, 2015). "The prevalence of SPINK1 mutations in patients with idiopathic chronic pancreatitis has been reported as between 16-23%, with a case series reporting that SPINK1 mutations were 16.9% more common in patients with chronic and recurrent acute pancreatitis than controls." (PMID 29515728, 2017). "In agreement with previous reports, we found that the severity of cerulein-induced acute pancreatitis was unaffected by heterozygous Spink1 deletion when the disease was elicited with transient hyperstimulation (10 hourly injections)." (PMID 38768901, 2024). "Prolonged but not transient cerulein stimulation resulted in increased intrapancreatic trypsin activity and more severe acute pancreatitis in Spink1-KOhet mice relative to the C57BL/6N control strain." (PMID 38768901, 2024). "In contrast, acute pancreatitis induced with limited cerulein hyperstimulation was unaffected by heterozygous Spink1 deletion, in agreement with recent observations that trypsin activity does not mediate pathologic responses in this model." (PMID 38768901, 2024). "A comprehensive systematic review and meta‐analysis of the genetic evidence for acute pancreatitis was conducted, and identified credible associations of SPINK1, ALDH2, IL1B, IL6 and IL18 with the risk of acute pancreatitis." (PMID 32011822, 2020). "The aim of this study was to determine the frequency of genetic mutations in SPINK1, CFTR and CTRC genes in patients with acute pancreatitis (AP), as well as to investigate their relation with the etiology and clinical course." (PMID 26100556, 2015). "Acute pancreatitis has been associated with mutations in CTR and SPINK-1 genes both in the general population and in HIV-infected patients." (PMID 23468971, 2013). "A review of nine studies with a total of 1493 patients and 2595 controls found a link between SPINK1-N34S in the allelic model and a higher risk of acute pancreatitis, mostly in Caucasians but not in Asians, which also makes this case interesting." (PMID 39687810, 2024). "Our results support the notion that transient cerulein hyperstimulation causes trypsin-independent acute pancreatitis where heterozygous loss of Spink1 has no impact on severity." (PMID 38768901, 2024). "However, a new finding was the fact that the mutation SPINK1 (hetero p.N34S), in combination with CTRC c.180C > T, can be responsible for a more severe course of acute pancreatitis." (PMID 28095786, 2017).
acute pancreatitis (continued). "Under these conditions, acute pancreatitis was significantly more severe in Spink1-KOhet mice relative to C57BL/6N animals, and intrapancreatic trypsin and chymotrypsin activities were also significantly higher in the Spink1-deficient mice when measured 30 minutes after the last injection." (PMID 38768901, 2024). "Here, we used hourly injections of cerulein (50 μg/kg) to elicit acute pancreatitis in C57BL/6N and Spink1-KOhet mice." (PMID 38768901, 2024). "The unexpected finding that heterozygous Spink1-deleted mice exhibited no change in severity of cerulein-induced acute pancreatitis was later confirmed by Rodger Liddle’s group." (PMID 38768901, 2024). "While the role of genetics in predisposition to acute recurrent and/or chronic pancreatitis of different etiologies has been the focus of many studies (PRSS1, PRSS2, SPINK1, CFTR, CLDN2, CAP1), ASNase-related acute pancreatitis have only started emerging recently." (PMID 35582721, 2019).